FLT3 (fms related receptor tyrosine kinase 3)
Diseases named in the same sentence as FLT3 in open-access papers (continued):
Sharing a sentence is not in itself a finding about the gene and the disease.
acute lymphoblastic leukemia (77 papers, 2011 to 2025). Leukemia with an acute onset, characterized by the presence of lymphoblasts in the bone marrow and the peripheral blood. "A total of eight lymphoid leukemia cell lines were positive for a mutation in FLT3, including one T lymphoblastic leukemia, two B lymphoblastic leukemia, two mature T and NK neoplasms, and three mature B cell neoplasms." (PMID 41287669, 2025). "A mediastinal biopsy was indicative of an early T-cell precursor acute lymphoblastic leukemia with FLT3 mutation." (PMID 36290900, 2022). "Currently, this is the first data on FLT3 mutations in Tunisian children with acute lymphoblastic leukemia (ALL)." (PMID 36407352, 2022). "This study was conducted to evaluate the frequency of FLT3-ITD mutation in Tunisian childhood acute lymphoblastic leukemia, and to correlate this mutation with prognostic parameters." (PMID 36407352, 2022). "FLT3 mutations are typically associated with AML but uncommonly with acute lymphoblastic leukemia (ALL)." (PMID 34299222, 2021). "Unfortunately, the possibility of starting gilteritinib as a pre-emptive strategy only in patients who manifest a minimal residual disease positivity after HSCT (similarly to acute lymphoblastic leukemia Philadelphia-positive) is hampered by technical difficulties to exactly quantify FLT3 mutation." (PMID 37297842, 2023). "In addition, 5–10% of patients with Myelodysplasia (MDS) and 1–3% of Acute Lymphoblastic Leukemia (ALL) patients have mutations in the FLT3 gene." (PMID 28538663, 2017). "Early T-cell precursor acute lymphoblastic leukemia (ETP-ALL) has been identified as high-risk subgroup of acute T-lymphoblastic leukemia (T-ALL) with a high rate of FLT3-mutations in adults." (PMID 23359050, 2013). "FLT3 ITD mutations rarely occur in adult acute lymphoblastic leukemias (ALL) of B-cell origin and childhood ALL." (PMID 21272320, 2011). "FLT3 encodes a receptor tyrosine kinase (RTK) that plays a key role in hematopoiesis, and is overexpressed in MLL-rearranged acute lymphoblastic leukemia." (PMID 41075061, 2025). "Early focus areas included “chemotherapy” and “acute lymphoblastic leukemia,” while recent trends highlight “minimal residual disease,” “stem cell transplantation,” and “FLT3,” indicating a shift toward advanced therapies and molecular research." (PMID 40034590, 2025). "Activating mutations in the fms-like tyrosine kinase 3 (FLT3) are present in 25%–30% of patients with AML, approximately 10% of patients with myelodysplastic syndrome (MDS), and 5–6% of patients with acute lymphoblastic leukemia (ALL)." (PMID 38950330, 2024). "Meanwhile, in acute lymphoblastic leukemia (ALL), the mutation rate of FLT3 varies from 4.7% to 6.8%." (PMID 39273530, 2024). "A comprehensive genomic (DNA-seq in 267 patients) and transcriptomic (RNA-seq in 160 patients) analysis of FLT3 in 342 childhood acute lymphoblastic leukaemia (ALL) patients was performed." (PMID 38049555, 2024). "Moreover, 80% of BCL11B-rearranged early T-cell precursor acute lymphoblastic leukemia (ALL) cases have activating FLT3 mutations." (PMID 38132393, 2023). "FLT3 is one of the major targets for AML therapy, and activating mutations of FLT3 are found in approximately one-third of AML and less than 3% of acute lymphoblastic leukemia patients." (PMID 35337118, 2022). "For example, PRMT1-mediated FLT3 arginine methylation exacerbates acute lymphoblastic leukemia progression." (PMID 36151091, 2022). "Mutations in RAS pathway proteins (e.g., KRAS, NRAS, FLT3, PTPN11, and NF1) are highly prevalent in acute lymphoblastic leukemia (ALL), with such mutations occurring in 40%–50% of pediatric B cell ALL cases." (PMID 35243242, 2022). "FLT3 mutations are in general rare in acute lymphoblastic leukemia (ALL)." (PMID 33003568, 2020). "Mutations in FLT3 are involved in AML (FLT3 +-AML) and, to a minor extent, in acute lymphoblastic leukaemia (ALL) as well." (PMID 29699481, 2018).
acute lymphoblastic leukemia (continued). "The second most common FLT3 mutations are missense point mutations in the tyrosine kinase domain which occur in approximately 5–10% of AML, 2–5% of MDS and 1–3% of acute lymphocytic leukemia (ALL) cases." (PMID 28498310, 2017). "UL-1 was the only cell line to upregulate FLT3, and increased FLT3 expression has been previously identified in canine a subset of acute lymphocytic leukemias and the GL-1 cell line." (PMID 27639374, 2016). "Mutations in FLT3, KRAS, NRAS, and BRAF genes have been observed with variable prevalence (5-20%) in acute myeloid (AML) and lymphoblastic leukaemias (ALL)." (PMID 24571676, 2014). "Gene expression analyses have shown that FLT3 is highly expressed in MLL-rearranged acute lymphoblastic leukemias." (PMID 21552520, 2011). "Transplantation of FLT3-ITD expressing bone marrow led to MPD, whereas transplantation of FLT3-TKD expressing cells led to a lymphoid disease with longer latency, consistent with the finding that TKD mutations are more common in acute lymphoblastic leukemia than AML." (PMID 35756660, 2022). "Apart from CML LSCs, the same strategy might be applicable for targeting LSCs in AML patients with FLT3-ITD mutation and Philadelphia positive acute lymphoblastic leukemia that express CD26." (PMID 33804056, 2021). "As for other lymphoblastic leukemias described, FLT3 itself is overexpressed in ETP-ALL." (PMID 23359050, 2013). "Similarly, FLT3-ITD mutations are largely restricted to subtypes of AML, and are rarely reported in cases of acute lymphoblastic leukemia (ALL)." (PMID 22643831, 2012). "Studies have explored CD5-CAR-NK cells and CD7-CAR-NK cells for T-cell acute lymphoblastic leukemia (T-ALL) treatment and FLT3-CAR-NK cells in B-cell acute lymphoblastic leukemia (B-ALL)." (PMID 39007146, 2024). "FLT3 is also highly expressed in KMT2Ar acute lymphoblastic leukemia (ALL), a disease that has been shown to undergo lymphoid-to-myeloid lineage switch following CD19-CAR-T cell therapy as a mechanism of antigen escape." (PMID 39095991, 2024). "FLT3 is an attractive therapeutic target in acute lymphoblastic leukemia (ALL) but the mechanism for its activation in this cancer is incompletely understood." (PMID 36104354, 2022). "Here we studied the possibility to induce NK cell ADCC against B-cell acute lymphoblastic leukemia (B-ALL) by Fc-optimized FLT3 antibody treatment." (PMID 31817795, 2019). "Ponatinib, a c-ABL1 inhibitor, is currently approved for CML and acute lymphoblastic leukemia (ALL) therapy, and it is also a fibroblast-macrophage colony-stimulating factor (FMSF)-like tyrosine kinase 3 (FLT3) inhibitor." (PMID 38023990, 2023). "FLT3-ITD is also present in 10% of pediatric AML, 1% of myelodysplastic syndrome (MDS) and 3% of acute lymphoblastic leukemia (ALL)." (PMID 31336846, 2019). "The majority of AMLs and acute lymphoblastic leukemias (ALL) have overexpression of FLT3." (PMID 29487300, 2018). "FLT3 mutations and overexpression have emerged as negative prognostic biomarkers in acute lymphoblastic leukemia (ALL) and acute myeloblastic leukemia (AML)." (PMID 27391351, 2016). "Currently, there is no published data on FLT3 mutations in Saudi acute lymphoblastic leukemia (ALL) patients." (PMID 24959335, 2014). "MRX2843, a dual Mer/Flt3 (fms-like tyrosine kinase 3) inhibitor (Mer IC50 = 1.2 nM), showed improved CNS penetration (brain/plasma ration = 0.4) and is currently in phase II trails for relapsed/refractory acute lymphoblastic leukemia (NCT04872478)." (PMID 40867624, 2025). "To control whether these cytotoxic effects are specific for AML cells with mutant FLT3, we incubated human leukemic cells with wild-type FLT3 (RS4-11 cells from a 32-year-old woman with acute lymphoblastic leukemia) with FK228 and AC220." (PMID 34665271, 2022). "This has spurred the progression of CAR NK cells that recognize alternative B-cell acute lymphoblastic leukemia (B-ALL) targets, such as FMS-like tyrosine kinase 3 (FLT3)." (PMID 36428748, 2022).
acute lymphoblastic leukemia (continued). "The majority of human acute leukemias, including 100% of B-cell lineage acute lymphoblastic leukemias (ALL), 27% of T-lineage ALL, and 89% of acute myelogenous leukemias (AML) overexpress FLT3." (PMID 21272320, 2011). "Unlike CD19 in acute lymphoblastic leukemia (ALL), FLT3 is also expressed at lower levels in normal hematopoietic stem and progenitor cells (HSPCs), raising concerns about on-target, off-tumor toxicity for CAR-based therapies." (PMID 41280924, 2025). "High expression of FLT3 is a common feature of AML and acute lymphoblastic leukemia (ALL)." (PMID 31731727, 2019). "The anti-SDF-1 effect of NOX-A12 was not limited to murine cells, as evidenced by its ability to reduce, however not abolish, SDF-1-induced migration of the human BCR-ABL-positive acute lymphoblastic leukemia (ALL) line, SUP-B15, and the human FLT3-ITD-positive line, MOLM14." (PMID 29299123, 2017).
acute leukemia (73 papers, 2010 to 2025). A clonal (malignant) hematopoietic disorder with an acute onset, affecting the bone marrow and the peripheral blood. "FMS-like tyrosine kinase 3 with internal tandem duplication (FLT3-ITD) mutation is a key driver of acute leukemia progression, strongly associated with poor survival and chemotherapy resistance." (PMID 40362245, 2025). "FLT3 inhibitor (tyrosine kinase inhibitor) and B-cell lymphoma-2 inhibitor coordinate and eliminate FLT3/ITD mutations of acute leukemia cells via B-cell lymphoma 2-like protein 11 activations." (PMID 36914737, 2023). "Patients with new acute leukemias of mixed or ambiguous lineage (MPAL/ALAL) should also be tested for FLT3 mutations at diagnosis, as FLT3 is mutated in a significant proportion of cases (from 12% overall, up to 47% in T/myeloid patients)." (PMID 38132393, 2023). "MLL fusions and the FLT3-ITD mutation are known oncogenic drivers of acute leukemias and are dependent on the activity of CDK9 and FLT3, respectively." (PMID 35267421, 2022). "Forty FLT3 mutations were detected among 105 acute leukemia cases with mutation frequency of 38.10%." (PMID 31518054, 2019). "Together, these experiments demonstrate the ability of ART-838 or AS to cause substantial in vivo inhibition of acute leukemias harboring clinically unfavorable FLT3/ITD or MLLr mutations." (PMID 26771236, 2016). "Internal tandem duplication mutations of the fms-like tyrosine kinase-3 (FLT3-ITD) portend poor prognosis in acute leukemias and have recently been found capable of predicting ED in pediatric patients with acute APL." (PMID 23936694, 2013). "To model the effects of NVP-BGT226 and NVP-BEZ235 on mutant-TK triggered AKT activation, we chose two well established acute leukemia cell lines harboring a FLT3 ITD mutation (MOLM14) or a BCR-ABL1 mutation (K562)." (PMID 23705826, 2013). "Recent work has shown that FLT3 activating mutations can collaborate with a Nup98-HoxD13 mutation to induce an aggressive acute leukemia." (PMID 22643831, 2012). "FMS-like tyrosine kinase 3 (FLT3) is a commonly mutated protein in a variety of human acute leukemias." (PMID 21272320, 2011). "Eighteen FLT3 mutations were discovered among 517 acute leukemia cases for an overall frequency of 3.5%." (PMID 20875128, 2010). "Furthermore, mice with both KMT2A PTD and FLT3 ITD develop acute leukemia, highlighting the role of cooperative mutations in leukemogenesis." (PMID 39766092, 2024). "In their recently published position statement paper, the acute leukemia working party of the EBMT recommended allogeneic HSCT in first CR for all FLT3-ITD mutated AML patients with the exception of NPM1 mutated/low FLT3-ITD allelic ratio individuals achieving an MRD-negative CR." (PMID 36831653, 2023). "FLT3 mutation testing may also be considered in other new acute leukemias of uncertain lineage if there are significant delays in receiving confirmation of the phenotype." (PMID 38132393, 2023). "CLSG/GCEL key questions and summary of recommendations for FLT3 mutation testing in acute leukemia." (PMID 38132393, 2023). "Interestingly, Foretinib is an ATP-competitive inhibitor of tyrosine kinases, and both acute leukemia cell lines with the lowest IC50 values to this drug carried FLT3 activating mutations (MONO-MAC-6, p.V592A; MOLM-13, ITD)." (PMID 35734412, 2022). "In mice, mIDH2R140Q in hematopoietic tissues was not sufficient for the development pf AML phenoype, suggesting the requirement of additional driver mutations, like overexpression of HoxA9 and Meis1a or mutations in FMS-like tyrosine kinase 3 (FLT3) to drive acute leukemia in vivo." (PMID 33898313, 2021). "Indeed, ART-838 was effective with IC50<1μM against every acute leukemia tested, including those harboring poor prognosis mutations such as MLLr and FLT3 internal tandem duplication (FLT3/ITD)." (PMID 26771236, 2016).
acute leukemia (continued). "We were able to directly cross-check the clinically most relevant RTK mutations in acute leukemia (i.e. FLT3-ITD, KIT D816V/Y, BCR/ABL1) transfected into an isogenic Ba/F3 background against a panel of leukemic cell lines harboring a corresponding RTK mutation." (PMID 23497317, 2013). "FLT3 appears to be a promising therapeutic target, in light of its upregulation in several forms of acute leukemia, and a deeper understanding of FLT3 mutations through valid experimental models could improve the development of more effective FLT3 inhibitors in overcoming DR." (PMID 40563676, 2025). "However, the FLT3-ITD mutation was needed for progression to acute leukemia with ETP-ALL phenotype." (PMID 34912707, 2021). "In recent studies leveraging acute leukemia PDX models, researchers have illuminated the potential of combined therapeutic strategies targeting multiple mutated proteins, notably FLT3 and associated pathways." (PMID 40510031, 2025). "The use of FLT3 inhibitors (FLT3i) for the treatment of acute leukemias mainly concerns AML, which represents nowadays a treatment paradigm for FLT3-mutated patients." (PMID 41154380, 2025). "Higher FLT3 expression levels are described and considered recurrent alterations in acute leukemias." (PMID 39711880, 2024). "Among these kinases, FLT3 is a member of class III receptor tyrosine kinase family which is abundantly expressed in individuals with acute leukemia." (PMID 38794229, 2024). "FLT3 plays a crucial role in regulating hematopoiesis and is commonly found to be overexpressed in the majority of acute leukemia patients." (PMID 38794229, 2024). "The clinical and biological impacts of these transcript isoforms are still not fully assessed; the same studies were focused on the association of these isoforms with FLT3-ITD, a genetic alteration found in acute leukemia." (PMID 38921185, 2024). "In this review, we describe relevant proliferative signals [driven by FMS-like tyrosine kinase 3 (FLT3)], molecular and cellular players involved in cell cycle progression/regulation and the related alterations characterizing acute leukemias." (PMID 36770891, 2023). "Co-treatment of midostaurin with 17-AAG (Hsp90 inhibitor) attenuated phospho-FLT3 and induced apoptosis in human acute leukemia cells MV4-11." (PMID 35267471, 2022). "FLT3-ITD patient samples and cell lines have increased expression of GLI2, and FLT3-ITD transgenic mice show rapid progression from myeloproliferation to acute leukemia when crossed with SmoM2 transgenic mice that have constitutive HH activation." (PMID 36091167, 2022). "VRP encoding the TAA, FLT3, which is a self-antigen known to be overexpressed in acute leukemias, was given to mice bearing FLT3-expressing tumors." (PMID 35686131, 2022). "Recently, we reported on the characterization of an Fc-optimized mAb, which targets FMS-like tyrosine kinase 3 (FLT3) expressed on the cell surface of leukemic cells in patients with acute leukemia." (PMID 33915811, 2021). "To examine the localization of endogenous FLT3, we performed confocal immunofluorescence microscopic analyses on human acute leukemia cell lines with an anti-FLT3 luminal-faced N-terminal region antibody." (PMID 34811450, 2021). "Ras pathway mutations are highly prevalent in relapsed acute leukemia, especially in pediatric AML where it can represent up to 30% of cases, as KRAS, NRAS, fms-like tyrosine kinase 3 (FLT3) or PTPN11 mutations." (PMID 32050659, 2020). "While FGFR1 was overexpressed in a variety of nonhematopoietic tumor types, PDGFRA was exclusively overexpressed in brain tumors, and FLT3 was exclusively overexpressed in acute leukemias." (PMID 31651965, 2019).